EPGN (epithelial mitogen)
Description:
Promotes the growth of epithelial cells. May stimulate the phosphorylation of EGFR and mitogen-activated protein kinases.
Synonyms: EPG; PRO9904; ALGV3072
Tractability: Antibody: UniProt places it where antibodies can reach, with high confidence; its Gene Ontology location is reachable by antibodies, with high confidence; UniProt predicts a signal peptide or a membrane-spanning region. PROTAC: ubiquitination databases record sites on it.
Gene: Protein-coding gene on chromosome 4 (74,308,470 to 74,316,789, forward strand). Ensembl gene ENSG00000182585.
Subcellular location: Membrane (Isoform 1); Membrane (Isoform 2); Secreted (Isoform 3); Secreted (Isoform 4); Secreted (Isoform 5); Secreted (Isoform 6)
Subcellular location (Human Protein Atlas): Cytosol; Nucleoplasm; Vesicles; Predicted to be secreted
Pathways (Reactome):
Signal Transduction: EGFR downregulation; EGFR interacts with phospholipase C-gamma; Estrogen-dependent nuclear events downstream of ESR-membrane signaling; Extra-nuclear estrogen signaling; GAB1 signalosome; GRB2 events in EGFR signaling; PI5P, PP2A and IER3 Regulate PI3K/AKT Signaling; PIP3 activates AKT signaling; RAF/MAP kinase cascade; SHC1 events in EGFR signaling; Signaling by EGFR
Disease: Constitutive Signaling by Aberrant PI3K in Cancer; Inhibition of Signaling by Overexpressed EGFR
Vesicle-mediated transport: Cargo recognition for clathrin-mediated endocytosis; Clathrin-mediated endocytosis
Gene Ontology:
Molecular function: epidermal growth factor receptor binding; growth factor activity; protein binding; receptor ligand activity
Biological process: angiogenesis; epidermal growth factor receptor signaling pathway; positive regulation of cell population proliferation; positive regulation of MAPK cascade; positive regulation of mitotic nuclear division; positive regulation of epithelial cell proliferation; cell surface receptor signaling pathway
Cellular component: plasma membrane; clathrin-coated endocytic vesicle membrane; extracellular region; membrane
Genetic constraint (gnomAD): Loss-of-function variants: 17 observed, 17.49 expected, observed/expected ratio (o/e) 0.97, 90% interval 0.66 to 1.46. The upper end of that interval is the gene's LOEUF score, 1.46, which puts it in group 6 of 6, group 1 being the genes least tolerant of losing a copy. Missense variants: 180 observed, 170.41 expected, observed/expected ratio (o/e) 1.06, 90% interval 0.94 to 1.2. Synonymous variants: 65 observed, 60.78 expected, observed/expected ratio (o/e) 1.07, 90% interval 0.88 to 1.32.
Homologues: Orthologues: chimpanzee EPGN (100% identical), macaque EPGN (98% identical), dog EPGN (85% identical), pig EPGN (83% identical), mouse Epgn (77% identical), rabbit EPGN (77% identical), rat Epgn (76% identical), guinea pig EPGN (65% identical), tropical clawed frog epgn (32% identical). Paralogues in human: EREG (29% identical), BTC (21% identical), HBEGF (21% identical), TGFA (20% identical), AREG (17% identical).
Diseases named in the same sentence as EPGN in open-access papers:
EPGN is named in the same sentence as 14 diseases in open-access papers, as found by Europe PMC text mining. Sharing a sentence is not in itself a finding about the gene and the disease. The quoted sentences say what the papers report.
cyst (3 papers, 2011 to 2014). A sac-like closed membranous structure that may be empty or contain fluid or amorphous material. "Indeed, we found strong expression of NQO1, SLPI, SPRR2, and EPGN in the affected epidermis and cyst epithelium of these patients." (PMID 24503019, 2014). "The consequent upregulation of SLPI, SPRR2, and EPGN could then contribute to cyst formation in the skin of MADISH patients by the observed interference with stratum corneum desquamation and epidermal barrier formation." (PMID 24503019, 2014). "Indeed, we detected strong expression of SPRR2, SLPI, EPGN and of the classical NRF2 target NQO1 in the epidermis and cyst epithelium of MADISH patients, with particularly strong staining of SPRR2, SLPI, and NQO1 in differentiated keratinocytes." (PMID 24503019, 2014).
cervical cancer (2 papers, 2021 to 2024). A primary or metastatic malignant neoplasm involving the cervix. "Further research should focus on understanding the molecular mechanisms underlying the relationships between EPGN, LCN10, TP73, and ICI therapy, and explore their therapeutic potential in cervical cancer treatment." (PMID 38933923, 2024).
dyslipidemia (1 paper, 2021). "Additionally, the expression of EPGN, LGR5, NCK1, PGRMC2, and VIP were also comfired at transcriptional using qPCR, indicating that those genes are closely linked to dyslipidemia in OSA." (PMID 34880901, 2021).
tumor (4 papers, 2019 to 2024). "EPGN is a ligand of epidermal growth factor receptor (EGFR), which was known to be related with EMT and tumor metastasis." (PMID 33318296, 2020). "Due to the pivotal roles of EPGN, LCN10, and TP73 in the TIME, we conducted an analysis of immune cell profiles in CESC to investigate the connection between IRGPI and the composition of tumor-infiltrating immune cells." (PMID 38933923, 2024). "However, it is difficult to extrapolate these results to the in vivo setting since EGFR might respond not only to EGF but also to TGF-α, AR, EPGN, BTC, HB-EGF and EREG, which are also increased in tumor tissues." (PMID 31921216, 2019).
cancer (2 papers, 2020 to 2024). A tumor composed of atypical neoplastic, often pleomorphic cells that invade other tissues. "As PD-L1 expression is commonly used as a criterion for determining whether cancer patients should undergo ICI treatment, we examined the correlation between PD-L1/PD-1 expression levels, risk scores, and the expression of EPGN, LCN10, and TP73." (PMID 38933923, 2024).
EPGN also shares sentences with these, for which no sentence is quoted: infection (2 papers); adenocarcinoma (1); bacterial infection (1); fungal infection (1); glioblastoma multiform (1); Hyperkeratosis (1); lung disease (1); lymph node (1); periodontitis (1).